RNU6-117P (RNA, U6 small nuclear 117, pseudogene)
Gene: Small nuclear RNA gene on chromosome 6 (106,738,948 to 106,739,054, reverse strand). Ensembl gene ENSG00000202285.
Homologues: Orthologues: chimpanzee U6 (99% identical), macaque U6 (93% identical), dog U6 (84% identical), rabbit U6 (75% identical), mouse Gm22965 (72% identical). Paralogues in human: RNU6-1152P (88% identical), RNU6-686P (87% identical), RNU6-211P (86% identical), RNU6-199P (85% identical), RNU6-41P (85% identical), RNU6-536P (85% identical), RNU6-562P (85% identical), RNU6-768P (85% identical), RNU6-820P (85% identical), RNU6-854P (85% identical), RNU6-1060P (84% identical), RNU6-116P (84% identical), and 1288 more.